STX3 (syntaxin 3)
Diseases named in the same sentence as STX3 in open-access papers:
STX3 is named in the same sentence as 53 diseases in open-access papers, as found by Europe PMC text mining. Sharing a sentence is not in itself a finding about the gene and the disease. The quoted sentences say what the papers report.
microvillus inclusion disease (7 papers, 2020 to 2024). Microvillus inclusion disease (MVID) is a very rare, severe, malabsorbative syndrome characterized clinically by protracted or intractable neonatal secretory diarrhea and histologically by inclusion bodies on the intestinal epithelium. "Biallelic STX3 variants were previously reported in five individuals with the severe congenital enteropathy, microvillus inclusion disease (MVID)." (PMID 33974130, 2021). "Besides, intestinal organoids were derived from patients with microvillus inclusion disease (MVIX) caused by homozygous truncating mutations of syntaxin-3 (STX3) gene." (PMID 33135109, 2020). "Microvillus inclusion disease (MVID) is a rare enteropathy caused by mutations in the MYO5B or STX3 gene." (PMID 34501384, 2021). "A severe form of hereditary diarrhea called microvillus inclusion disease (MVID, OMIM 251850) was described in five individuals with biallelic mutations of the syntaxin 3 gene (STX3, OMIM 600876) by us and by others." (PMID 33974130, 2021). "One such example is microvillus inclusion disease (MVID), a congenital enteropathy characterized by early-onset diarrhea, caused by mutations in myosin 5b (MYO5B), STX3 or syntaxin binding protein 2 (STXBP2)." (PMID 38799985, 2024). "Epithelial cells and nervous system expressed STX3 (OMIM 600876) has recently been reported as the pathogenic gene of microvillus inclusion disease (MVID) with or without nystagmus." (PMID 33251218, 2020).
breast carcinoma (4 papers, 2022 to 2025). "The STX3 gene may contribute to carcinogenesis via up- or down-regulation in various cancer, promoting breast cancer cell growth." (PMID 41149035, 2025). "In breast cancer, STX3 has been identified as a promoter of growth in human breast cancer cells, and its presence in tumor tissues could act as an indicator of a poor prognosis." (PMID 38014487, 2023). "The roles of Syntaxin 3(STX3) acts as an oncogenic protein in human breast cancer." (PMID 35057823, 2022). "Initial studies suggested that STX3 overexpression might inhibit breast cancer cell proliferation." (PMID 39085482, 2024). "Syntaxin 3 (STX3), a protein encoded by the human STX3 gene, has garnered attention in breast cancer research due to its significant upregulation in both gene expression and protein levels within human breast cancer tissues in comparison with adjacent non-cancerous tissues." (PMID 39085482, 2024).
retinal degeneration (4 papers, 2010 to 2025). Degeneration of the retina. "Stx3 accumulates in the outer segment in models of retinal degeneration caused by defects in the BBSome, but not in Ift20 and Ift172 knockouts." (PMID 39871753, 2025). "Given the rapidly devastating consequences of biallelic STX3/stx3 loss-of-function in both humans and mice, we wondered whether monoallelic Stx3 loss-of-function might lead to retinal degeneration later in life." (PMID 37609371, 2023).
Retinal dystrophy (4 papers, 2021 to 2024). Retinal dystrophy is an abnormality of the retina associated with a hereditary process. "Biallelic loss-of-function mutations in the syntaxin 3 gene have been linked to a severe retinal dystrophy in humans that presents in early childhood." (PMID 37609371, 2023). "Together, our results provide a link between STX3 loss-of-function variants and a human retinal dystrophy." (PMID 33974130, 2021). "Interestingly, this is the first demonstration of non-syndromic retinal dystrophy linked to STX3, a gene that has thus far been only implicated in the syndrome of retinal dystrophy with microvillus inclusion." (PMID 38098057, 2023). "Recently, biallelic loss-of-function mutations in the human retinal-specific syntaxin 3 spliceform, syntaxin 3B (STX3B), have been linked to an early-onset severe retinal dystrophy in young children." (PMID 37609371, 2023). "If the mutations are located in exons that are conserved between syntaxin 3A and the retinal-specific syntaxin 3 spliceform, syntaxin 3B, the children additionally exhibited an early onset severe retinal dystrophy." (PMID 37609371, 2023). "Depending on the genomic site of a human loss-of-function STX3 variant, it can cause MVID, the novel intestinal-retinal syndrome reported here or, hypothetically, an isolated retinal dystrophy." (PMID 33974130, 2021). "However, when an exon shared between syntaxin 3A and 3B contained the pathogenic mutation, these young MVID patients additionally exhibited an early-onset, severe retinal dystrophy (EOSRD), highlighting the importance of syntaxin 3B for human vision." (PMID 39408994, 2024).
retinal disease (3 papers, 2021 to 2024). "An additional charge for the future will be to develop methods to exploit the unusual calcium-dependent regulation of syntaxin 3 functionality for therapeutic gain in retinal disease and in disorders of other syntaxin 3-expressing cells." (PMID 39408994, 2024). "Beyond disease connections to STX3 mutations, the interaction of STX3 with PRPH2 and RHO suggest a broader impact on retinal diseases." (PMID 38799985, 2024).
lymph node metastasis (2 papers, 2023 to 2024). "The results showed that high STX3 mRNA expression was correlated with the presence of lymph node metastasis and advanced pathologic stage." (PMID 38014487, 2023). "Interestingly, STX3 expression was significantly elevated in PCa patients with low differentiation, stage III + IV, and lymph node metastasis compared to those with high differentiation, stage I + II, and absence of lymph node metastasis." (PMID 39085482, 2024).
Sjögren’s syndrome (2 papers, 2018). "In labial salivary glands from the patients with Sjögren’s syndrome, syntaxin-4 and VAMP-8 expression were decreased, whereas syntaxin-3 expression was increased." (PMID 29358308, 2018). "In patients with primary Sjögren’s syndrome, STX4 gene and protein expression is decreased in labial salivary glands, while STX3 gene and protein expression is increased, compared to healthy individuals." (PMID 30336591, 2018). "The intracellular expression patterns of STX3 and STX4 also dramatically change in patients with Sjögren’s syndrome." (PMID 30336591, 2018).
Visual impairment (2 papers, 2021 to 2023). "Interestingly, of the identified human STX3 mutations associated with visual impairment to-date, all have been biallelic loss-of-function mutations." (PMID 37609371, 2023).
adenovirus infection (1 paper, 2016). "By labeling cells at early times (< 16 hrs) after adenovirus infection, we found that plasma membrane Stx3 was first detected at axon tips, and not at the proximal axonal region, suggesting that it is preferentially inserted at or near the growing tip." (PMID 27662481, 2016).
Alzheimer disease (1 paper, 2021). A progressive, neurodegenerative disease characterized by loss of function and death of nerve cells in several areas of the brain leading to loss of cognitive function such as memory and language. "Three of these genes: STX3, LACTB2 and PLIN2 had novel significant associations with Alzheimer’s disease." (PMID 33959712, 2021). "STX3, one of the novel TWAS significant genes was dropped after conditional analysis along with three of the genes in Alzheimer’s disease risk loci: FNBP4, MYBPC3 and MS4A6A." (PMID 33959712, 2021).
Chlamydia infection (1 paper, 2019). "To determine whether the plasma membrane SNAREs SNAP-23, Syntaxin 3, and Syntaxin 4 play a role during Chlamydia infection, we first assessed their localization during infection." (PMID 32025513, 2019). "Since these SNAREs are recruited to the inclusion, we tested whether Chlamydia infection impacts Syntaxin 3/SNAP-23 and Syntaxin 4/SNAP-23 t-SNARE complex formation." (PMID 32025513, 2019). "Thus, we investigated whether SNAP-23, Syntaxin 3 or Syntaxin 4 play a role in LD dynamics during Chlamydia infection." (PMID 32025513, 2019).
cholestasis (1 paper, 2021). Impairment of the bile flow caused by obstruction within the liver, or outside the liver in the bile duct system. "Cholestasis has not been reported from the very few MVID patients with STX3 or STXBP2 mutations so far." (PMID 33924896, 2021).
colon cancer (1 paper, 2023). "Western blot was performed on ten Golgi proteins (GBF1, GM130, Golgin97, TGN38, GRASP65, GRASP55, BLZF1, STX3, STX6, and GOLPH3) in small-cell lung cancer (SCLC), leukemia, colon cancer, and GIST cell lines expressing WT-KIT or MT-KIT." (PMID 37704840, 2023).
cyst (1 paper, 2024). A sac-like closed membranous structure that may be empty or contain fluid or amorphous material. "The apical targeting protein Syntaxin-3 also immunolocalized to the apical domain of cyst-lining epithelial cells." (PMID 38339183, 2024). "Since we found Syntaxin-3 to be apically localized in both normal human tubules and cyst epithelium, this discrepancy does not alter the interpretation of our results." (PMID 38339183, 2024).
developmental delay (1 paper, 2021). "In addition to visual impairment and MVID, global developmental delay was present in a few subjects with pathogenic STX3 variants." (PMID 33974130, 2021).
diabetes (1 paper, 2023). "The results revealed that IRAK1, TRAF6, NUMB, and STX3 are direct targets of miR-146 in the context of diabetes." (PMID 37560309, 2023).
Diarrhea (1 paper, 2024). Abnormally increased frequency (usually defined as three or more) loose or watery bowel movements a day. "STX3 is a soluble N-ethylmaleimide-sensitive factor attachment protein receptor (SNARE) protein, and STX3 loss causes metabolic acidosis and chronic diarrhea." (PMID 38683247, 2024).
esophageal squamous cell carcinoma (1 paper, 2023). Esophageal squamous cell carcinoma (ESCC) is a type of esophageal carcinoma (EC) that can affect any part of the esophagus, but is usually located in the upper or middle third. "Association between the expression of STX3 mRNA and clinicopathological parameters of 176 patients with esophageal squamous cell carcinoma." (PMID 38014487, 2023). "Prognostic factors for overall survival in esophageal squamous cell carcinoma patients in STX3 mRNA dataset (n = 176)." (PMID 38014487, 2023). "High STX3 mRNA and protein levels in surgical specimens were significantly correlated with poor prognosis in two independent cohorts of esophageal squamous cell carcinoma patients." (PMID 38014487, 2023). "STX3 overexpression in esophageal squamous cell carcinoma tissues may be a prognostic biomarker." (PMID 38014487, 2023).
eye movement disorders (1 paper, 2020). "Our results provide insights into the role of MUNC18-1-syntaxin 3B interaction in retinal function, and propose retina synaptic transmission as a novel target for treating these eye movement disorders." (PMID 33251218, 2020).
latent infection (1 paper, 2022). "HCMV-miR-US33-5p targets the 3′-untranslated region (UTR) of HCMV US29 and host STX3, inhibiting viral DNA replication by suppressing US29 and STX3 expression, and promoting HCMV latent infection." (PMID 35596131, 2022).
Legionella infection (1 paper, 2023). "In addition, it has been demonstrated that deubiquitination of Sec22b by LotB/Ceg23 during Legionella infection causes disassociation of Stx3 from Sec22b on LCVs, indicating that the ubiquitination status of Sec22b may be important for promoting this noncanonical pairing." (PMID 37882795, 2023).
liver disease (1 paper, 2015). "As the liver disease in mice with Rab8 deficiency or MVID patients with Syntaxin 3 defects has not been described thus far, it is possible that Rab8 and Syntaxin 3 role in this pathway is not as important in hepatocytes as it is in the intestine." (PMID 26116792, 2015). "Liver disease has not yet been described in patients with Syntaxin 3 defects." (PMID 26116792, 2015).
macular edema (1 paper, 2026). "Levels of STX3 and NOTCH2, proteins involved in retinal function, were correlated with a diagnosis of macular edema, a record of a visual field exam, and a prescription for latanoprost, highlighting protein-EHR alignment." (PMID 41918763, 2026).
metabolic acidosis (1 paper, 2025). "Chronic diarrhoea is linked to familial hemophagocytic lymphohistiocytosis type 5 and metabolic acidosis in patients with syntaxin-binding protein 2 (STXBP2/MUNC18-2) mutation and to neurological impairments in patients with syntaxin 3 (STX3) mutation, respectively." (PMID 40310351, 2025).
neuritis (1 paper, 2017). A neuropathy arising from inflammation of one or more nerves. "It has been demonstrated that DHA stimulates the production of syntaxin 3 (STX3), a plasma membrane protein that has an important role in the growth of neuritis in PC12 cells and hippocampal neurons cultures." (PMID 28752333, 2017).
Nystagmus (1 paper, 2020). Rhythmic, involuntary oscillations of one or both eyes related to abnormality in fixation, conjugate gaze, or vestibular mechanisms. "Given that the disrupted interaction between p.His16Arg mutant and syntaxin 3B may contribute to the impaired neurotransmission in retina, how the retinal defect in signal transduction causes congenital nystagmus?" (PMID 33251218, 2020). "We propose that the altered interaction between MUNC18-1 and syntaxin 3B may impair neurotransmitter release at ribbon synapses, eventually leading to the abnormal retinal neurotransmission and nystagmus." (PMID 33251218, 2020).
ovarian tumor (1 paper, 2024). "In addition, it has been reported that deubiquitination of Sec22b by LotB, an ovarian tumor-related proteases (OTU) family DUB, stimulates the dissociation of STX3 from Sec22b, suggesting that Sec22b ubiquitination is required for such an interaction." (PMID 38836877, 2024).
Polyhydramnios (1 paper, 2022). The presence of excess amniotic fluid in the uterus during pregnancy. "Together, the occurrence of polyhydramnios associated with MVID was not restricted to either the MYO5B, STX3, or STXBP2 variants." (PMID 35893420, 2022).
prostate carcinoma (1 paper, 2024). A carcinoma that arises from epithelial cells of the prostate gland. "To explore STX3’s influence on prostate cancer cell behaviors like proliferation, migration, and invasion, we established PCa cell lines with STX3 knockdown." (PMID 39085482, 2024). "However, this study marks the first exploration of STX3’s involvement in prostate cancer (PCa), emphasizing the need for additional validation." (PMID 39085482, 2024).
infection (7 papers, 2017 to 2024). The state of being infected such as from the introduction of a foreign agent such as serum, vaccine, antigenic substance or organism. "In support of this hypothesis, we observed a significant increase in the association of Stx3 with ubiquitinated Sec22b in our biochemical as well as infection experiments." (PMID 37882795, 2023). "To test the importance of SNAP-23, Syntaxin 3, and Syntaxin 4 during infection, we depleted HeLa cells of either of these SNAREs using the CRISPR/Cas9 system." (PMID 32025513, 2019). "Next, we investigated the impact of SNAP-23, Syntaxin 3, and Syntaxin 4 depletion on LD production during infection." (PMID 32025513, 2019). "Infection-stimulated ubiquitination of Sec22b appears to be important for the unconventional pairing event since deubiquitination of Sec22b by LotB could disassociate STX3 from Sec22b." (PMID 38836877, 2024). "Indeed, our recent study revealed that Lug15, a novel L. pneumophila E3 ligase, is responsible for Sec22b ubiquitination during infection and promotes the noncanonical interaction between STX3 and Sec22b." (PMID 38836877, 2024). "Expression of CMA genes during infection of these cell lines was also examined (right 12 lanes), and demonstrated that reduction in GRIM-19 level did not influence the level of transcription of any of the four CMA genes tested (TPM3, STX3, Dystroglycan 1 [DAG1], and Heme-binding protein 1 [HEBP1])." (PMID 34346763, 2021).
gastrointestinal disorder (2 papers, 2023 to 2024). "In humans, biallelic loss-of-function mutations in syntaxin 3A, a syntaxin 3 splice form expressed widely throughout the body outside of the retina, gives rise to a devastating gastrointestinal disorder that presents in infancy." (PMID 37609371, 2023).
neurological disease (2 papers, 2020 to 2022). "Like the previous comparison, several of these transcripts, such as CELF5, DEPTOR, DLG2, OPTN and STX3, have been linked to brain functions and neurological disorders, supporting the fact that these hnRNP proteins can work in a network to regulate at least specific sets of targets." (PMID 36267332, 2022).
tumor (2 papers, 2023 to 2024). "High STX3 mRNA expression in tumor tissues showed a significant correlation with pathologic lymph node involvement and advanced pathologic stage when analyzing the association between STX3 mRNA expression and clinicopathologic factors." (PMID 38014487, 2023). "In conclusion, suppressing STX3 expression led to diminished PCa cell growth in nude mice, resulting in decreased tumor volume and burden on the animals." (PMID 39085482, 2024). "STX3 knockdown in PC-3 cells, analyzed for effects on cell behaviors and tumor growth in mice, highlighted its potential therapeutic impact." (PMID 39085482, 2024). "Patients were categorized into two groups based on the third quartile cutoff of STX3 mRNA expression levels in tumor tissue, for the purpose of evaluating the prognostic value of STX3 mRNA expression." (PMID 38014487, 2023). "Next, we performed immunohistochemistry (IHC) of tumor tissue microarrays (TMAs) obtained in another set of ESCC patients to examine the prognostic significance of STX3 protein expression." (PMID 38014487, 2023). "We next performed a subgroup analysis according to age, sex, the administration of NAC, lymph node involvement, pathological stage, and tumor differentiation status to assess the impact of STX3 mRNA expression levels on the prognosis of OS." (PMID 38014487, 2023). "Immunohistochemical staining confirmed STX3 expression in tumor tissues." (PMID 39085482, 2024). "Additionally, patients with high STX3 expression exhibited larger tumor volumes and higher Gleason scores." (PMID 39085482, 2024). "Associations between Syntaxin 3 (STX3) expression and malignancy have been reported in several tumor types but not in ESCC." (PMID 38014487, 2023). "Therefore, STX3 protein expression was detected by IHC using surgically resected specimens without shrinkage or disappearance of tumor." (PMID 38014487, 2023).
gastrointestinal disease (1 paper, 2024). A disease that occurs in the gastrointestinal system, excluding the hepatobiliary system. "Biallelic loss-of-function mutations in the human syntaxin 3 gene affecting syntaxin 3A were identified that gave rise selectively to microvillus inclusion disorder (MVID), a severe, inherited gastrointestinal disease that presents in early infancy and has a poor prognosis." (PMID 39408994, 2024). "Mutations that selectively impair syntaxin 3B function are predicted to result in vision defects in the absence of gastrointestinal disease." (PMID 39408994, 2024).
retinopathy (1 paper, 2024). "Notably, STX3 stands as the sole syntaxin linked to retinopathy-causing mutations, evident in the retinal phenotype observed in MVID patients carrying STX3 mutation." (PMID 38799985, 2024).
STX3 also shares sentences with these, for which no sentence is quoted: cancer (3 papers); Intellectual disability (2); autism (1); bowel dysfunction (1); cataract (1); Cohen syndrome (1); congenital cataracts (1); congenital enteropathy (1); diabetic kidney disease (1); enteropathy (1); HCMV infection (1); leukemia (1); lung adenocarcinoma (1); lung carcinoma (1); malaria (1); myotonic dystrophy type 1 (1); neurodegenerative disease (1); small cell lung carcinoma (1).